INS (insulin)
Diseases named in the same sentence as INS in open-access papers (continued):
Sharing a sentence is not in itself a finding about the gene and the disease.
metabolic syndrome (continued). "Pharmacological inhibition of ABHD6 causes beneficial metabolic effects in mice such as enhancement of insulin secretion and energy expenditure, thus qualifying ABHD6 as a promising target for the treatment of the metabolic syndrome and its comorbidities." (PMID 36005632, 2022). "Subjects with features of metabolic syndrome had higher levels of C-peptide, GIP, insulin, leptin, PAI-1, and lower levels of ghrelin, whereas overweight and obese individuals had increased levels of GIP, leptin, glucagon, and decreased levels of ghrelin." (PMID 35409072, 2022). "Additional studies to unravel the effects of NPGL on insulin sensitivity and glucose tolerance using the ICR strain will help to elucidate the biological mechanisms of metabolic syndromes in heterogeneous populations." (PMID 35742932, 2022). "The increased levels of HOMA-IR and circulating insulin, total and LDL cholesterol, and triglycerides showed that O adolescents had reduced insulin sensitivity together with a certain degree of dyslipidemia." (PMID 36613584, 2022). "Nevertheless, one has to keep in mind that testosterone replacement therapy in hypogonadal diabetic males is related to an improvement of insulin sensitivity in patients with T2DM, metabolic syndrome or both." (PMID 34223999, 2022). "Participants also showed sustained improvements in the glycemic profile, including HbA1c, glucose, insulin and HOMA-IR, as well as, in metabolic syndrome characteristics, including waist circumference, triglycerides, blood pressure and HDL-c." (PMID 36532543, 2022). "Study showed olaznpine inhibited GLP1/GLP1R expressions in small intestine and pancreas, consequently lead to decreased insulin gene, including GLUT4, and ultimately dyslipidemia and glucose excursions." (PMID 35067163, 2022). "Together, these pancreatic hormones regulate blood glucose homeostasis, food intake and insulin responses and are therefore integral to understanding T2DM and metabolic syndrome." (PMID 36034454, 2022). "This includes commonly investigated parameters relating to dyslipidemia (serum TG, FFA, cholesterol) content, insulin or glucose tolerance tests, body weight and adiposity." (PMID 36499091, 2022). "The 6-month WL intervention resulted in reduced BMI (−13.7%), improved insulin sensitivity (HOMA-IR, −46.1%), and reduced levels of circulating hsCRP (−39.9%), indicating metabolic syndrome reversal." (PMID 34066026, 2021). "Interestingly, a seven day intervention in patients with metabolic syndrome found a significant decline in blood glucose and an increase in insulin, which suggests in the short-term, supplementation may improve insulin sensitivity, but this does not appear to translate to long-term benefits." (PMID 34604282, 2021). "As expected, NAFLD patients had increased BMI, fasting glucose, and insulin concentrations, as well as elevated ALT and GGT activities; all markers of metabolic syndrome and NAFLD." (PMID 34943103, 2021). "However, many studies have indicated that IR could promote atherosclerosis not only through mechanisms that involve systemic factors, such as dyslipidemia, hypertension, and a proinflammatory state, but also through the effect of perturbed insulin signaling at the level of the intimal cells." (PMID 34167539, 2021). "The two publications are not directly discussing the association between insulin and depression, but use the form of a review to summarize the relationship between exercise and depression, and the relationship between exercise and metabolic syndrome represented by abnormal insulin levels." (PMID 34366917, 2021). "Older age, higher WC, higher insulin, lower FSH, and lower SHBG were predictive for dyslipidemia among Chinese women with PCOS." (PMID 34977197, 2021).
metabolic syndrome (continued). "Our findings corroborate the hypothesis that high selenium status disturbs insulin metabolism leading to hyperinsulinemia, but the effect on glucose is not as strong, as it can be mitigated when controlling strong risk factors for T2DM such as body weight and metabolic syndrome." (PMID 34262926, 2021). "The current study showed that age, WC, insulin, FSH, and SHBG were predictors for dyslipidemia in women with PCOS." (PMID 34977197, 2021). "The ad libitum feeding promoted an obese phenotype over time in both groups with increased plasma levels of glucose (p = 0.005), fructosamine (p < 0.001), insulin (p = 0.03), and HOMA-IR (p = 0.02), whereas the clinical markers of dyslipidemia were unaffected." (PMID 34066330, 2021). "Gck translocation mainly mediated whole-body glucose homeostasis, even the insulin-stimulated hepatic glycogen synthesis, which means that the activation of Gck could accelerate the synthesis process of hepatic glycogen and alleviate dysglycemia and dyslipidemia in liver." (PMID 33936248, 2021). "AUC of age, WC, insulin, FSH, and SHBG for dyslipidemia were 0.571, 0.683, 0.698, 0.574, and 0.698, respectively." (PMID 34977197, 2021). "TG, glucose (GLU), high-density lipoprotein cholesterol (HDL-C), low-density lipoprotein cholesterol (LDL-C), and hormone (insulin, leptin, and adiponectin) levels were analyzed to assess the effects of PLA2 on metabolic syndrome." (PMID 33947969, 2021). "In our model of metabolic syndrome, we observed a reduction of senescent markers together with an increase of HDL-C and improved insulin sensitivity of EAT." (PMID 34638943, 2021). "IR is a key factor in the pathogenesis of metabolic syndrome; we then investigated the effect of SYT on IR by measuring fasting insulin, HOMA-IR, and ITT." (PMID 34658856, 2021). "After birth, infants from GDM mothers are likely to develop childhood obesity, metabolic syndrome, T2DM, and impaired insulin secretion." (PMID 34603565, 2021). "CCL4 inhibition mice also had decreased levels of phosphorylated IRS-1 in both skeletal muscle and liver tissues compared to those in the untreated metabolic syndrome mice, implying the beneficial effects of CCL4 inhibition on insulin signaling." (PMID 33968046, 2021). "Anthropometric variables, glucose, insulin, triglycerides (TG), high-density lipoprotein cholesterol (HDL-C), systolic (SBP) and diastolic blood pressure (DBP) and metabolic syndrome (MetS) were also analyzed." (PMID 32033484, 2020). "Other significant factors in this model include age, BMI, hypertension, dyslipidemia, previous cardiovascular disease history, RAS inhibitor use, insulin use, and GRACE score." (PMID 32317703, 2020). "As OxS and inflammation are key inducers of IR and other metabolic affections of the Metabolic Syndrome (MetS), we decided to evaluate GMP’s capacity to regulate some key proteins of the insulin signaling pathway." (PMID 32331475, 2020). "Prior history of dyslipidemia—meaning preoperative statin use—had a protective effect against perioperative MAE and stroke occurrence, whereas insulin use negatively affected 4-year survival." (PMID 30909911, 2019). "In obese and overweight patients with metabolic syndrome, the expression of NAMPT increases in the plasma and simulates the effect of insulin." (PMID 30755828, 2019). "In a subsequent study on 38 Caucasian men with metabolic syndrome, lean donor FMT also resulted in a significant improvement in peripheral insulin sensitivity at 6 weeks." (PMID 30719428, 2019). "In our study, the increase of total cholesterol, insulin, and glucose in the blood of HFD-fed mice indicated a metabolic syndrome in the mice." (PMID 31470507, 2019). "For example, a high responder in cardiorespiratory fitness does not necessarily mean any given individual will be a high responder in metabolic syndrome or the constituent elements thereof (HDL-C, triglycerides, fasting insulin or visceral adiposity)." (PMID 31798463, 2019).
metabolic syndrome (continued). "Cardiometabolic outcomes included weight, waist- and hip circumference, body mass index, systolic and diastolic blood pressure, fasting glucose and insulin, HOMA-IR, hs-CRP, lipids and metabolic syndrome." (PMID 29324776, 2018). "However, treatment with myoIns has not been found to lower insulin and glycaemia in all patients with metabolic syndrome, strongly suggesting that sensitivity to inositol supplementation of insulin-resistant subjects may depend on still unknown additional factors." (PMID 30595691, 2018). "Thiazolidinediones (TZDs) are a class of antidiabetic drugs that increase systemic insulin sensitivity in tissues of animal models and humans with T2DM and the metabolic syndrome." (PMID 30524482, 2018). "In conclusion prepubertal males born with IUGR increased weight, insulin and leptin and decreased adiponectin, as compared to males born AGA, emerge as early metabolic syndrome characteristics." (PMID 30356143, 2018). "Pharmacological stimulation of AMPK provokes many benefits like improvement of insulin sensitivity and glucose homeostasis, making it an attractive target for T2DM and metabolic syndrome." (PMID 30542284, 2018). "The improved dyslipidemia in diabetic rats treated with NAC (DM+NAC) can be explained by the greater insulin secretion in the presence of this antioxidant, since insulin decreases blood sugar levels and lipolysis in adipose tissue." (PMID 29796316, 2018). "For example, sipoglitazar was used to treat patients with metabolic syndrome and T2DM through improving peripheral insulin sensitivity, lowering the lipid content of bodies and reducing body weight." (PMID 30060458, 2018). "We measured body composition (Dual X-ray Absorptiometry), uric acid, blood pressure, lipid profile, gamma-glutamyl-transferase (GGT), glucose, and insulin, and calculated the HOMA and metabolic syndrome z-score." (PMID 30103429, 2018). "In this cohort, it may be that fasting insulin and C-peptide are more closely linked to other variables included in the multivariate models and with the components of the metabolic syndrome, whereby not being independently associated with CHD once adjusted in the multivariate models." (PMID 30555835, 2018). "By inducing an insulin-resistant state in all major insulin target organs, including the ECs, liver, and skeletal muscles, FFAs contribute to the progression of T2DM, HTN, dyslipidemia and nonalcoholic fatty liver disease (NAFLD)." (PMID 28750629, 2017). "GEB increased serum insulin levels dose-dependently and GEB-H mostly enhanced dyslipidemia in ORX rats." (PMID 28607572, 2017). "Given the interplay among hypertension, inflammation, and metabolic syndrome, the objective of the study was to test the effect of EWH on differentiation, insulin signaling and inflammatory responses in 3T3-F442A pre-adipocytes." (PMID 28972997, 2017). "We also investigated the effect of age and RE-T upon biomarkers of metabolic health, including fasting glucose/insulin (and thus HOMA-IR), in addition to markers of dyslipidemia, i.e., plasma LDL/HDL cholesterol and triglycerides." (PMID 28878131, 2017). "Individuals with dyslipidemia and/or IGR had higher levels of fasting glucose and fasting insulin than NGT/NL group." (PMID 28199386, 2017). "Given the interplay among hypertension, inflammation, oxidative stress and metabolic syndrome, the objective of the study was to test the EWH on differentiation, insulin signaling and inflammatory responses in 3T3-F442A pre-adipocytes." (PMID 28972997, 2017). "Moreover, IR in the context of Metabolic syndrome may be present specifically in the insulin signal transduction pathway related to glucose metabolism within a tissue but not in other intracellular elements of this pathway related to other functions such as lipid metabolism or proliferation." (PMID 29280741, 2017).
metabolic syndrome (continued). "Increasing tertiles of TG:HDL-C ratio showed significant increase in mean insulin level (p = 0.03), HOMA-IR (p = 0.04) and significantly higher number of children with acanthosis nigricans and metabolic syndrome." (PMID 28059134, 2017). "FMT in humans with metabolic syndrome has beneficial effects on the recipients' microbiota composition (increase in SCFA-producing bacteria), with a concomitant improvement in insulin sensitivity." (PMID 28058051, 2016). "The analysed population presented similar levels of glucose, insulin, HOMA-IR, low-density lipoprotein cholesterol (LDL-C), and triglyceride as the controls, but the incidence of metabolic syndrome was significantly increased." (PMID 27091671, 2016). "Adiponectine, which is an adipocytokine preventing metabolic syndrome or atherosclerosis, activates AMPK in skeletal muscle and improves insulin sensitivity." (PMID 27348124, 2016). "The effects of statins on insulin secretion and the stimulus-secretion coupling of the beta cells are uncertain, but in the Metabolic Syndrome in Men (METSIM) cohort statins, including rosuvastatin, reduce insulin secretion." (PMID 26986474, 2016). "The metabolic syndrome animals also exhibited a significant increase in fasting blood glucose (FBG) and fasting insulin (FINS); in addition, lipid metabolism disorders were manifested as fatty and hyperlipidemia." (PMID 26652604, 2015). "Although there were no corresponding changes in glucose tolerance or circulating insulin levels, we predict that the BDE-47 treated Pten−/− mice would develop other signs of the metabolic syndrome later in life." (PMID 26217518, 2015). "Blood pressure, body weight, body fat, triglycerides, insulin, HOMA-index, albuminuria, and TNF-α were increased in ovariectomized metabolic syndrome rats (p < 0.001)." (PMID 26491436, 2015). "Furthermore, the recent findings in the population-based Metabolic Syndrome in Men (METSIM) cohort revealed that statin-treated subjects encountered a 46% increased risk of T2D; two mechanisms were principally involved, i.e., decrease in both insulin sensitivity and secretion." (PMID 26486974, 2015). "This up-regulated insulin-Akt signaling is diminished by aging and a HFD, which ultimately proceeds to metabolic syndrome." (PMID 26316333, 2015). "The areas under the ROC curve of HbA1c, insulin, glycemia, and HOMA-IR for metabolic syndrome were 0.670, 0.770, 0.754, and 0.796, respectively." (PMID 26241903, 2015). "The data are available demonstrating that MC3R and MC4R agonists and DA2R agonist bromocriptine improved insulin sensitivity and prevented the metabolic abnormalities in DM2 and metabolic syndrome." (PMID 26124826, 2015). "Mice made obese on the 60% diet displayed elevated glucose, insulin, HOMAIR scores, and leptin and lower concentrations of adiponectin, which together are characteristics of metabolic syndrome." (PMID 25072025, 2014). "Participants with metabolic syndrome had a higher mean CRP (5.3 versus 4.4 mg/dL; P = 0.45), insulin (18 versus 11 uIU/mL; P = 0.07), and BMI (32 versus 30 kg/m2; P = 0.45) compared to their counterparts." (PMID 25136359, 2014). "In univariable analyses, bilirubin was inversely related to age, BMI, smoking status, waist circumference, insulin, HOMA-IR, total cholesterol, triglycerides, and the presence of metabolic syndrome." (PMID 24595410, 2014). "An elevated IR, a cut-off value 2.60 is commonly used, denotes an insufficiency of insulin-mediated glucose uptake and is one of the central features of T2DM and also one of the key features of the metabolic syndrome." (PMID 24695378, 2014). "The metabolic syndrome (MetS) has been identified as a constellation of metabolic and nonmetabolic disorders related to defects in insulin sensitivity that lead to a high risk for the development of type 2 diabetes and cardiovascular disease (CVD)." (PMID 24800228, 2014).
metabolic syndrome (continued). "Thus, the positive effects of liraglutide on glucose tolerance in this model of metabolic syndrome are best described by a direct effect on pancreatic beta-cells that seems to promote augmented exocytosis rather than promoting beta-cell proliferation and/or acting on peripheral insulin action." (PMID 24423471, 2014). "The score incorporates simple variables such as the presence of the metabolic syndrome and T2DM, fasting serum insulin, aspartate aminotransferase (AST) level, and AST/alanine aminotransferase (ALT) ratio." (PMID 25141008, 2014). "We propose that this insulin/glucagon synergism plays a role in mediating the elevation in FGF21 production during starvation and conditions related to metabolic syndrome." (PMID 24733293, 2014). "Additional pathophysiological mechanisms, which link metabolic syndrome to cancer, are elevated adipokines levels, IGF, the mitogenic action of insulin, and increased levels of reactive oxygen species." (PMID 23781121, 2013). "FXR-/- mice display both impaired glucose tolerance and decreased insulin sensitivity, therefore, the findings suggest that FXR activity can be a potential biomarker of the development and treatment of metabolic syndrome and T2D." (PMID 24252331, 2013). "The simultaneous reduction in glucose, insulin, and IGF1 and the increase in IGFBP1 seen postoperatively, and remaining at follow-up, strengthen the possible reversibility of the metabolic syndrome coupled with PHPT." (PMID 24026893, 2013). "Sixteen weeks of HFD feeding induced conditions which closely resemble metabolic syndrome: HFD-fed mice gain significantly more weight, have higher serum glucose, insulin, triglycerides and FFAs levels." (PMID 23342074, 2013). "Since a low serum testosterone level induces metabolic syndrome and increases visceral fat due to a poor response to insulin and a low basal metabolic rate, patients treated with CMA for a long-term need a periodic checkup of metabolic syndrome." (PMID 23762042, 2013). "The results of our study showed that obese and even overweight children had dyslipidemia (high TC, TG, LDL-C, insulin and low HDL-C), especially in boys." (PMID 23984682, 2013). "As in other studies, overweight individuals had higher serum concentrations of TG, insulin, and HOMA-IR, the criteria used in the diagnosis of the metabolic syndrome as proposed by the WHO." (PMID 23762051, 2013). "Conversely, increased physical activity is associated with reduced abdominal fat, reduced intrahepatic fat, and improved insulin sensitivity, all factors that are present in individuals with NAFLD and the metabolic syndrome." (PMID 23576902, 2013). "Serum insulin, glucose, diastolic blood pressure, TG, leptin and CRP were significantly higher in metabolic syndrome group compared to obese and control groups." (PMID 22691465, 2012). "The NAFLD liver fat score includes, as variables, the presence of metabolic syndrome and T2DM, fasting serum insulin, serum AST, and the AST/ALT ratio." (PMID 22110476, 2012). "Administration of insulin itself would be beneficial in the patients admitted to the ICU by reducing inflammation and dyslipidemia." (PMID 24665266, 2012). "After several generations of selection and breeding, LCR rats developed numerous markers of metabolic syndrome, including, elevated LDL cholesterol, blood pressure, triglycerides, fasting glucose, insulin, C-reactive protein, and visceral adiposity." (PMID 20584300, 2010). "By contrast, we included four variables (TC, TG, LDLC and HDLC) to quantify dyslipidemia and included AUC for PG and PI during OGTT at 0-30 min and 0-120 min for insulin secretion." (PMID 20181263, 2010). "It is now widely recognised that insulin resistant states, such as T2DM, cardiovascular disease and the metabolic syndrome, are characterised by a low-grade systemic inflammation, as well as inflammatory changes in adipose tissue." (PMID 20353583, 2010).